IGF1R (insulin like growth factor 1 receptor)
Diseases named in the same sentence as IGF1R in open-access papers (continued):
Sharing a sentence is not in itself a finding about the gene and the disease.
melanoma (continued). "We demonstrate that IGF1R and IR are activated in response to chronic dabrafenib and trametinib resistance in BRAF-mutant melanoma and are differentially expressed in parental and resistant cell lines." (PMID 34831014, 2021). "IGF1R (insulin-like growth factor I receptor), another receptor tyrosine kinases found to be upregulated in our sample, has been found to have anti-apoptotic properties and to be overexpressed in multiple cancers including melanoma, where may represent a potential therapeutic target." (PMID 35052351, 2021). "In our study, we found that in melanoma cells with reduced HAT1 expression levels, IGF1R levels were upregulated, leading to the activation of MAPK/Ras signaling pathway and conferring BRAFi resistance." (PMID 32371878, 2020). "Most of the shared genes (40 genes) were downregulated including MMP16, IGF1R, FLOT1 and CEP19 and are functionally involved in several types of cancers, including melanoma." (PMID 32613561, 2020). "We found that treatment with either the ERK or IGF1R inhibitors was able to restore sensitivity to vermurafenib in both HAT1-knockdown and HAT1-KO BRAFi-resistant melanoma cells, in both the soft-agar assay and in the clonogenic long-term survival assay." (PMID 32371878, 2020). "IGF1R rs2229765 (p = 0.004) and IGF1 rs1520220 (p = 0.005) showed significant genotypic and recessive differences between melanoma cases and healthy controls." (PMID 32150843, 2020). "We also found that the pharmacological targeting of the MAPK signaling pathway via IGF1R and ERK1/2 inhibitors was able to partially restore the sensitivity of HAT1-knockdown and HAT1-KO melanoma cells to BRAFi." (PMID 32371878, 2020). "IGF1R expression has been related to both the intrinsic mitochondrial pathway, as observed in colon cancer cells, and the TNF-TRAIL pathway in melanoma cells." (PMID 32899449, 2020). "IGF1R and CD44 are overexpressed in most advanced melanomas so we designed chemotherapeutic nanoparticles to target those receptors." (PMID 30824801, 2019). "Here, through an unbiased screening approach, we identified SIRT6-mediated transcriptional regulation of IGFBP2, and consequent activation of IGF-1R/AKT, to play a role in melanoma MAPKi resistance." (PMID 30143629, 2018). "IGF-1R downregulation synergizes with MEK1/2 inhibition, by removing a crucial back-up pathway available to melanoma cells." (PMID 29946532, 2018). "To directly investigate the effects of biased IGF-1R down-regulation on MEK1/2 inhibition, we evaluated the ability of melanoma cells to survive in the presence of MEK1/2 inhibitors (U0126)." (PMID 29137261, 2017). "Studies showed that receptor tyrosine kinases (RTK) such as PDGFRβ, IGF1R, EGFR and c-Met were overexpressed in melanoma cells." (PMID 28708099, 2017). "their cognate receptors (IR, IGF1R, IGF2R and heterologous pairs) and binding proteins (IGFBPs) are important determinants of melanoma disease progression." (PMID 28223541, 2017). "We found high levels of RNA of the corresponding cognate receptors – IR, IGF1R, and IGF2R in all the four melanoma cells studied here." (PMID 28223541, 2017). "As we report here, the melanoma cells indeed appear to be in a state of heightened insulin/IGF sensitivity via abundant expression of IR, IGF1R and IGF2R as seen in all four melanoma cells in this study." (PMID 28223541, 2017). "In agreement with recent comprehensive reports of IGF gene expressions in melanoma, we found low levels of IGF1 and very high levels (25-fold greater than GHR) of IGF1R and IGF2R expression (Figure 5a1)." (PMID 28223541, 2017). "Briefly, biased or neutral, balanced IGF-1R down-regulation was induced by treating the melanoma cells grown in complete media, with Nutlin-3, CP or IGF-1R siRNA, the IGF-1R inhibitors were removed, and the cells treated with and without U0126." (PMID 29137261, 2017).
melanoma (continued). "Taken together, our results advocate for the concept that IGF-1R targeting synergizes with MEK1/2 inhibition, by removing a crucial back-up pathway available to melanoma cells." (PMID 29137261, 2017). "Therefore, we examined if inhibition of FASN could suppress IGF-1R expression in melanoma." (PMID 27323414, 2016). "We also found that epidermal growth factor receptor (EGFR), insulin-like growth factor-1 receptor (IGF-1R) and CRAF were over-expressed in VemR A375 melanoma cells." (PMID 27448964, 2016). "In summary, we reported that IT exerted anti-melanoma activities, and these effects were partially due to inhibition of FASN/IGF-1R/STAT3 signaling." (PMID 27323414, 2016). "IGF-1R is expressed by all the melanoma cell lines and FGFR1 is highly expressed in 7 out of the 9 analyzed melanoma cell lines." (PMID 27102439, 2016). "We demonstrated the co-expression of RUNX2 with IGF-1R, EGF-R, PDGFRβ and AXL using ShRNA RUNX2-expressing melanoma cells and showed co-expression of RUNX2 with AXL in human melanoma samples." (PMID 27102439, 2016). "We showed that epidermal growth factor receptor (EGFR), insulin-like growth factor-1 receptor (IGF-1R) and CRAF were over-expressed in VemR A375 melanoma cells." (PMID 27448964, 2016). "Acquired resistance to BRAF inhibitors in melanoma can be overcome by targeting MEK and IGF-1R/PI3K simultaneously." (PMID 27764776, 2016). "It has to be stressed that in our experiments we do never observe increased phosphorylation of other RTKs previously reported to be involved in the activation of survival pathways in melanoma cells, such as PDGFR and IGF1R." (PMID 26208478, 2015). "We previously showed that IGF-1R depletion blocks survival of BRAF mutant and wild-type (WT) melanoma cells, and enhances chemosensitivity." (PMID 26497996, 2015). "While AG1024 is a specific IGF-1R and IR inhibitor, it has been shown that AG1024 had an additional target in melanoma cells upstream of the Erk2 kinase." (PMID 23696913, 2013). "Pharmacological inhibition of IGF1R pheno-copied the decrease in migration seen following mir-376a and mir-376c over-expression, suggesting that down-modulation of the IGF1R signaling pathway may be responsible for the observed anti-migratory effect of these miRNAs in melanoma cell lines." (PMID 22747855, 2012). "In the tumors we analyzed, Igf1 was exclusively expressed in WT myeloid cells, but not in KO myeloid cells, while its receptor, Igf1r, was highly expressed in WT melanoma cells compared to KO melanoma cells." (PMID 41429766, 2025). "In the international Genes, Environment, and Melanoma study (GEM) dataset, the variants of rs1520220 in IGF1 and rs2229765 in IGF1R were significantly related to CM risk, but not in the Gene Environment Association Studies Initiative (GENEVA) dataset." (PMID 38892441, 2024). "IGF1R is overexpressed in melanoma and plays an oncogenic role by mediating tumor proliferation, motility, and protection from apoptosis, yet the relationship between E_349 and IGF1R gene was not supported by our A375 H3K27ac HiChIP." (PMID 37904237, 2023). "IGF1R, RIPK1, and PSEN2 are already known to contribute to vemurafenib resistance, suggesting that our new analysis method using v reliably identified hits whose ablation can sensitize melanoma to vemurafenib." (PMID 36829149, 2023). "Meanwhile, it has been demonstrated that miRNA-139 could bind to its target gene igf1r (insulin-like growth factor receptor type 1) to regulate the PI3K/AKT signaling pathway, which in turn controls the proliferation and spread of malignant melanoma cells." (PMID 36765276, 2023). "To further understand the biological connection between PTEN and Entpd5/IGF1R pathway, we first assessed the expression levels of ATF6 in melanoma cells carrying the various PTEN mutants by western blot; ATF6 expression was reduced in PTEN WT cells, but enhanced in PTEN ΔLP cells." (PMID 36824269, 2023).
melanoma (continued). "HAT1 downregulation is associated with non-responsiveness of BRAFi and MEKi in melanoma patients, and HAT1 depletion drives resistance to BRAFi vemurafenib and dabrafenib by upregulating MAPK via IGF1R in melanoma cells." (PMID 35966590, 2022). "In melanoma, the histone deacetylase sirtuin 6 (SIRT6)-mediated epigenetic modulation of the insulin-like growth factor 1 receptor (IGF1R)-protein kinase B (AKT) pathway results in the downregulation of autophagy in the early stage and an upregulation in the metastatic stage." (PMID 36003368, 2022). "They prepared HA NPs containing either IGF-1 to target IGF1R expressing melanomas or HA NPs not containing IGF-1." (PMID 35890401, 2022). "Treatment-naïve melanoma cells were sensitive to IGF1-R inhibition but ERK1/2i-resistant cells much more so, like their increased sensitivity to ERK5 pathway inhibition; indeed, ERK5 activation in resistant cells was IGF1-R-dependent." (PMID 35903549, 2022). "Nevertheless, the use of IGF-1R-targeting agents has not been evaluated in canine melanomas, neither in vitro nor in vivo." (PMID 33664868, 2021). "In our MN models, the activation of pAkt T308 by mTOR kinase inhibition, similar to melanoma cells, is mediated by IGF1R/IR; however, unlike melanoma, pAkt S473 remains fully inhibited by mTOR kinase inhibition in MN cells." (PMID 33273014, 2021). "In addition to IGF1R itself, gene encoding the FURIN protease, which is required for surface presentation of IGF1R, also had a higher essentiality in NRAS‐mutant melanoma cell lines compared cells with WT NRAS." (PMID 33073517, 2020). "A closer look revealed that the essentiality of IGF1R was significantly higher in NRAS‐mutant cell lines compared with NRAS‐WT background and also generally in BRAF WT melanoma cell lines, which is mainly composed of NRAS and HRAS mutants, compared with the BRAF V600E mutants." (PMID 33073517, 2020). "Introduction of miR-7 decreases the expression levels of EGFR, IGF-1R, CRAF in vitro as well as in Vemurafenib-resistant cells in melanoma xenograft mice models, which indicates that EGFR, IGF-1R, and CRAF are the target genes of miR-7 that are associated with the acquired resistance to BRAFi." (PMID 32054078, 2020). "By decreasing the expression levels of EGFR, IGF-1R, CRAF, miR-7 could inhibit the activation of the MAPK and PI3K/AKT pathways and reverse melanoma cell resistance to BRAFi." (PMID 32054078, 2020). "In this study, we incorporated Tris DBA-Pd into hyaluronic acid containing nanoparticles, either containing IGF-1 to target IGF1R expressing melanomas, or hyaluronic acid particles not containing IGF-1." (PMID 30824801, 2019). "Furthermore, in vivo and in vitro studies using IGF-1R antibodies, small molecule inhibitors, and antisense technology have shown that IGF-1R is functionally essential for melanoma cell growth and proliferation." (PMID 29946532, 2018). "Interestingly, we observed consistent expression of GH transcript in the melanoma cells as well as marked modulation of the IGF receptors and binding proteins (IGF1R, IGF2R, IR, IGFBP2, IGFBP3) and the oncogenic HGF-MET mRNA, in response to excess GH or GHRKD." (PMID 28223541, 2017). "Furthermore, WP760 downregulated IGF1R and upregulated PLK2 expression in most of the tested melanoma cell lines." (PMID 28417283, 2017).
melanoma (continued). "In cases of melanoma, RTKs such as VEGF receptor (VEGFR), fibroblast growth factor receptors (FGFR), hepatocyte growth factor receptor (HGFR), Insulin-like growth factor-1 receptor (IGF1R), and macrophage-stimulating protein receptor are activated through autocrine signaling." (PMID 27051190, 2016). "miR-7 could decrease the expressions of EGFR, IGF-1R and CRAF and further suppressed the activation of MAPK and PI3K/AKT pathways in VemR A375 melanoma cells." (PMID 27448964, 2016). "Finally, we showed a dramatic up regulation of RUNX2 expression with concomitant up-regulation of EGFR, IGF-1R and AXL in melanoma cells resistant to the BRAF V600E inhibitor PLX4720." (PMID 27102439, 2016). "Introduction of miR-7 mimics could markedly decrease the expressions of EGFR, IGF-1R and CRAF and further suppressed the activation of MAPK and PI3K/AKT pathway in VemR A375 melanoma cells." (PMID 27448964, 2016). "It is possible that the effect of RUNX2 on IGF1R protein expression does not occur at the transcriptional effect in 1205LU melanoma cells." (PMID 27102439, 2016). "Interestingly, disruption of the protein interaction between FAK and IGF-1R by a small molecule (INT2-31) induced apoptosis and cell cycle arrest, inhibited AKT phosphorylation in vitro and in tumors, and decreased growth of melanoma xenografts." (PMID 27102439, 2016). "IGF1R activation was reported in a panel of 25 melanoma cell lines derived from primary and metastatic lesions and a comprehensive analysis of RTK activation in human melanoma samples and cell lines identified autocrine signaling through IGF-1R." (PMID 27102439, 2016). "Our studies indicated that miR-7 could decrease the expression of EGFR, IGF-1R and CRAF and partly reverse the resistance to BRAFi in VemR melanoma cells, further suppressed the tumor growth in VemR melanoma xenografted mice model." (PMID 27448964, 2016). "For example, Villanueva and colleagues showed that, upon prolonged B-Raf inhibition, several melanoma cell lines displayed increased phosphorylation and expression of insulin-like growth factor 1 (IGF-1) receptor (IGF-1R) as well as enhanced phosphorylation of Akt." (PMID 27342992, 2016). "In addition, many studies have shown that IGF-1R depletion reduces the survival of BRAF-mutant and wild-type melanoma cells, and increases their chemosensitivity." (PMID 27764776, 2016). "In our study, IGF-1R-inhibited melanoma cells showed enhanced TMZ-induced apoptosis, relatively minor at 24–48 hr, more substantial 72 hr post-TMZ in vitro, and much more striking in melanoma xenografts after 5 days of TMZ and 3 days of OSI-906." (PMID 26497996, 2015). "Indeed, stable expression of mir-376a and mir-376c in melanoma cells led to a decrease in IGF1R mRNA and protein, and a luciferase reporter assay indicated that the 3'UTR of IGF1R is a target of both mir-376a and mir-376c." (PMID 22747855, 2012). "Notably, we demonstrate that PTEN phosphatase negatively regulates the protein N-glycosylation and folding promoter Entpd5 and the Entpd5/IGF1R pathway through Atf6 transcriptional regulation, identifying an important new mechanism by which PTEN inhibits melanoma metastasis." (PMID 36824269, 2023). "We also examined the ATF6 expression in human melanoma by immunohistochemistry using serial tissue microarray sections compared with PTEN, Entpd5 and IGF1R, and found that the ATF6 expression negatively correlated with PTEN expression, while positively with Entpd5 and IGF1R." (PMID 36824269, 2023). "A query of human tumor transcriptomic data for 471 melanoma patients from The Cancer Genome Atlas (TCGA) dataset revealed a positive correlation of IGF1 and ABCC9, ABCG1, ABCB1, and ABCC4 with GHR expression, and ABCC1 with both GHR and IGF1R expression, supporting our observations." (PMID 35865483, 2022).
melanoma (continued). "Conversely, small-molecule inhibitors of IGF1R triggered adherens junction formation between A375 cells even in the presence of serum, demonstrating that the absence of IGF1 signaling is both necessary and sufficient to elicit the behavioral changes observed in melanoma cells." (PMID 36229674, 2022). "Because there are no FDA-approved/brain penetrant IGF1R inhibitors, we used ceritinib, a noncanonical drug against IGF1R as proof of principle and noted its effectiveness against melanoma cells in this LMD model with acquired resistance to MAPK inhibitors (as occurs clinically)." (PMID 35213727, 2022). "Interestingly, miR-7 could reverse vemurafenib resistance in melanoma cell lines that overexpress EGFR, IGF-1R, and CRAF." (PMID 34948154, 2021). "In addition, because increased IGF1R expression levels were identified in the nCounter PanCancer Pathway Panel for Gene Expression, in both HAT1-knockdown and HAT1-KO BRAF-mutant melanoma cells, we analyzed the mRNA levels as well as protein levels of phospho- and total IGF1R in these samples." (PMID 32371878, 2020). "Moreover, we found that GCNT2/I-branched glycans decreased IGF-1 and RGD ligand binding activity on melanoma cells, suggesting that GCNT2/I-branches may modulate IGF1R and fibronectin: integrin signaling through modulation of ligand binding capacity." (PMID 30135430, 2018). "Together, these data indicate that SIRT6 haploinsufficiency allows BRAFV600E melanoma cells to survive in the presence of MAPKi by increasing IGFBP2 expression, which in turn activates IGF-1R/IR and downstream AKT signaling, that can be blocked by IGF-1R/IR inhibition." (PMID 30143629, 2018). "However, to our surprise, we did not observe any Gal-3-dependent IGF1R- or integrin-ECM-mediated signaling differences in melanoma cells expressing i-linear or I-branched polyLacNAc glycans." (PMID 30135430, 2018). "Indeed, the increased activation of insulin-like growth factor 1 receptor (IGF1R) by IGF1 can activate the RAF-MEK-ERK and/or PI3K-AKT pathways and may play a role in the development of melanoma resistance." (PMID 28708099, 2017). "We subsequently used small molecular inhibitors of EGFR (gefitinib), IGF-1R (linsitinib), and CRAF (GW5074), as single agent or in combination to further verify whether these genes really participate in BRAFi resistance in VemR A375 melanoma cells." (PMID 27448964, 2016). "Since EGFR, IGF-1R and CRAF have been known to be the key components of RTK-RAS-RAF-MEK-ERK (MAPK) and/or PI3K/AKT signaling pathways, we further determined if single or combined inhibition of EGFR, IGF-1R and CRAF could suppress the activation of MAPK and PI3K/AKT signaling in VemR melanoma cells." (PMID 27448964, 2016). "The administration of AG-1024 to melanoma cells over-expressing either mir-376a or mir-376c did not lead to a further decrease in their migration (results not shown), suggesting that the IGF1R axis could not be further modulated to decrease migration." (PMID 22747855, 2012). "Furthermore, several small-molecule and antibody-based inhibitors of IGF1R and the PI3K/AKT/mTOR pathway are currently being tested in the clinic, highlighting the potential translatability of combining these drugs with BRAF/MEK inhibitor therapy for the treatment of melanoma LMD." (PMID 38866016, 2024). "Furthermore, by decreasing the expression levels of EGFR, IGF-1R and CRAF, miR-7 could inhibit the activation of RAS/RAF/MEK/ERK (MAPK) and PI3K/AKT pathway and partially reverse the resistance to BRAFi in VemR A375 melanoma cells." (PMID 27448964, 2016). "An important protein of the Ras‐signalling pathway identified within these clusters was the receptor tyrosine kinase IGF1R, for which several drugs already exist, but are not used in the context of NRAS‐mutant melanoma to the best of our knowledge." (PMID 33073517, 2020). "In melanoma, ∆Ex2/3p73, but not ∆Np63α, mediates STAT3 (Tyr705) phosphorylation in an EPLIN/IGF-1R-dependent manner." (PMID 31569642, 2019).